XPO1 (exportin 1)
Description:
Mediates the nuclear export of cellular proteins (cargos) bearing a leucine-rich nuclear export signal (NES) and of RNAs. In the nucleus, in association with RANBP3, binds cooperatively to the NES on its target protein and to the GTPase RAN in its active GTP-bound form (Ran-GTP). Docking of this complex to the nuclear pore complex (NPC) is mediated through binding to nucleoporins. Upon transit of a nuclear export complex into the cytoplasm, disassembling of the complex and hydrolysis of Ran-GTP to Ran-GDP (induced by RANBP1 and RANGAP1, respectively) cause release of the cargo from the export receptor. The directionality of nuclear export is thought to be conferred by an asymmetric distribution of the GTP- and GDP-bound forms of Ran between the cytoplasm and nucleus. Involved in U3 snoRNA transport from Cajal bodies to nucleoli. Binds to late precursor U3 snoRNA bearing a TMG cap. (Microbial infection) Mediates the export of unspliced or incompletely spliced RNAs out of the nucleus from different viruses including HIV-1, HTLV-1 and influenza A. Interacts with, and mediates the nuclear export of HIV-1 Rev and HTLV-1 Rex proteins. Involved in HTLV-1 Rex multimerization.
Synonyms: Exp1; CRM1; CRM-1; emb
Tractability: Small molecule: an approved drug acts on it; a structure with a bound ligand is known; a high-quality ligand is known; it has a binding pocket of medium quality. PROTAC: ubiquitination databases record sites on it; its protein half-life has been measured; a small molecule that binds it is known.
Safety:
Unwanted effects reported when the protein is acted on. In parentheses: how it was acted on, where the effect was seen, and who reports it.
hepatotoxicity (source: ClinPGx)
liver injury (source: ClinPGx)
Gene: Protein-coding gene on chromosome 2 (61,476,032 to 61,538,753, reverse strand). Ensembl gene ENSG00000082898.
Subcellular location: Cytoplasm; Nucleus, nucleoplasm; Nucleus, Cajal body; Nucleus, nucleolus
Subcellular location (Human Protein Atlas): Nuclear membrane; Nucleoplasm; Cytosol; Primary cilium; Primary cilium tip; Vesicles
Pathways (Reactome):
Cell Cycle: Amplification of signal from unattached kinetochores via a MAD2 inhibitory signal; Cyclin A/B1/B2 associated events during G2/M transition; EML4 and NUDC in mitotic spindle formation; Mitotic Prometaphase; Resolution of Sister Chromatid Cohesion; Separation of Sister Chromatids
Signal Transduction: Deactivation of the beta-catenin transactivating complex; Downregulation of TGF-beta receptor signaling; Estrogen-dependent nuclear events downstream of ESR-membrane signaling; MAPK6/MAPK4 signaling; RHO GTPases Activate Formins
Disease: Maturation of DENV proteins; Maturation of hRSV A proteins; NEP/NS2 Interacts with the Cellular Export Machinery; Rev-mediated nuclear export of HIV RNA
Cellular responses to stimuli: Heme signaling
Developmental Biology: Transcriptional and post-translational regulation of MITF-M expression and activity
Gene expression (Transcription): NPAS4 regulates expression of target genes
Metabolism of RNA: HuR (ELAVL1) binds and stabilizes mRNA
Gene Ontology:
Molecular function: nuclear export signal receptor activity; protein binding; DNA-binding transcription factor binding; protein domain specific binding; small GTPase binding
Biological process: nucleocytoplasmic transport; protein export from nucleus; regulation of proteasomal ubiquitin-dependent protein catabolic process; ribosomal large subunit export from nucleus; ribosomal small subunit export from nucleus; ribosomal subunit export from nucleus; ribosome biogenesis; mRNA export from nucleus; cellular response to salt; cellular response to triglyceride; intracellular protein transport; negative regulation of transcription by RNA polymerase II; response to xenobiotic stimulus
Cellular component: annulate lamellae; cytoplasm; cytosol; kinetochore; membrane; nucleolus; nucleoplasm; protein-containing complex; ribonucleoprotein complex; nuclear envelope; Cajal body; nucleus
Genetic constraint (gnomAD): Loss-of-function variants: 5 observed, 127.09 expected, observed/expected ratio (o/e) 0.0393, 90% interval 0.02 to 0.083. The upper end of that interval is the gene's LOEUF score, 0.083, which puts it in group 1 of 6, group 1 being the genes least tolerant of losing a copy. Missense variants: 484 observed, 1,255.3 expected, observed/expected ratio (o/e) 0.39, 90% interval 0.36 to 0.42. Synonymous variants: 404 observed, 406.08 expected, observed/expected ratio (o/e) 0.99, 90% interval 0.92 to 1.08.
Cancer hallmarks: proliferative signalling (promotes); escaping programmed cell death (promotes)
Homologues: Orthologues: macaque XPO1 (100% identical), chimpanzee XPO1 (99% identical), dog XPO1 (99% identical), pig XPO1 (99% identical), rabbit XPO1 (99% identical), mouse Xpo1 (98% identical), rat Xpo1 (98% identical), guinea pig XPO1 (97% identical), zebrafish xpo1b (96% identical), tropical clawed frog xpo1 (94% identical), Drosophila melanogaster emb (71% identical), Caenorhabditis elegans xpo-1 (52% identical). Paralogues in human: XPO5 (17% identical).
Diseases named in the same sentence as XPO1 in open-access papers:
XPO1 is named in the same sentence as 191 diseases in open-access papers, as found by Europe PMC text mining. Sharing a sentence is not in itself a finding about the gene and the disease. The quoted sentences say what the papers report.
multiple myeloma (80 papers, 2014 to 2026). "Similarly, XPO1 is overexpressed in a number of human cancers such as gastric, oesophageal, bladder, and multiple myeloma and increased XPO1 expression has been associated with poor survival outcome." (PMID 33438820, 2021). "Selinexor has expanded the treatment horizon in myeloma by selectively inhibiting the nuclear export receptor Exportin-1 (XPO1) and disrupting the nucleocytoplasmic flow, inducing cell cycle arrest and apoptosis in cancer cells." (PMID 40136679, 2025). "XPO1, a nucleocytoplasmic shuttling protein, is overexpressed in multiple myeloma, playing a critical role in exporting tumour suppressor proteins (TSPs) and oncoprotein mRNA from the nucleus to the cytoplasm." (PMID 40687450, 2025). "XPO1 inhibitors have emerged as a novel treatment strategy for relapsed or refractory multiple myeloma, particularly in patients with triple-class refractory disease." (PMID 40687450, 2025). "Selinexor is an anticancer agent approved for the treatment of multiple myeloma and lymphoma, targeting exportin 1 (XPO1) to selectively inhibit nuclear export." (PMID 40733127, 2025). "Aiming to improve the outcome of relapsed and refractory MM patients, Selinexor has entered the drug arsenal of myeloma therapy through the implementation of a novel therapeutic approach by selectively inhibiting the nuclear export receptor Exportin-1 (XPO1)." (PMID 40136679, 2025). "Another novel agent under study is selinexor(an exportin-1 or XPO1 inhibitor), which has shown some activity in advanced ALamyloidosis and is in an early-phase trial for relapsed disease​." (PMID 41524065, 2025). "Inhibiting XPO1 by blocking topoisomerases in the nucleus can re-sensitize myeloma cells to the effects of anthracyclines and etoposide." (PMID 39050883, 2024). "XPO1 inhibitor has been approved for treating multiple myeloma and can sensitize NEPC and SCLC to chemotherapy in preclinical models." (PMID 39372390, 2024). "Selinexor is a selective inhibitor of XPO1 inhibitor and has been approved for multiple myeloma and diffuse large B-cell lymphoma." (PMID 38756650, 2024). "XPO1 exports topoisomerases from the nucleus to the cytoplasm, and this effect is stronger when myeloma cells are present at high density." (PMID 39050883, 2024). "Many cancers present with an elevated expression of XPO1, such as multiple myeloma, glioma, lung and breast." (PMID 39682167, 2024). "XPO1 inhibitor has been approved in treating relapsed and refractory multiple myeloma and relapsed diffuse large B-cell lymphoma, and has the potential for treating stomach cancer." (PMID 38554776, 2024). "KPT-330, a small molecule inhibitor of XPO1, is approved for treating relapsed multiple myeloma and diffuse large B-cell lymphoma." (PMID 38653804, 2024). "Through our computational process, we nominated selinexor, an XPO1 inhibitor approved to treat multiple myeloma (MM) for TNBC." (PMID 39682167, 2024). "Similar results were also obtained after treatment with selinexor, a highly selective and covalent XPO1 inhibitor approved by FDA to treat multiple myeloma." (PMID 37497004, 2023). "Overexpression of XPO1 has been demonstrated in myeloma cell lines as well as in myeloma cells from patients and was a rationale for testing of the XPO1-inhibitor selinexor in patients." (PMID 35643867, 2022). "XPO1 is overexpressed in many cancers including multiple myeloma (MM), and this overexpression of XPO1 enables cancer cells to escape TSP-mediated cell cycle arrest and apoptosis." (PMID 34802051, 2022).
multiple myeloma (continued). "Eltanexor (KPT-8602) is a novel second-generation XPO1 inhibitor currently under investigation in preclinical and early clinical settings for several cancer entities (colorectal, multiple myeloma, myelodysplastic syndrome, ALL subtypes, etc.)." (PMID 36140245, 2022). "Combining XPO1 inhibitors with other effective antimyeloma agents and cellular immunotherapy was expected to be complementary to existing therapies for multiple myeloma, as well as for other neoplasms." (PMID 34925019, 2021). "The overexpression of XPO-1 in myeloma cells, as in most cancer cells, makes selinexor a promising targeted therapy for MM patients." (PMID 34660279, 2021). "In the phase 3 BOSTON study, patients with multiple myeloma (MM) after 1–3 prior regimens were randomized to once‐weekly selinexor (an oral inhibitor of exportin 1 [XPO1]) plus bortezomib‐dexamethasone (XVd) or twice‐weekly bortezomib‐dexamethasone (Vd)." (PMID 34062004, 2021). "XPO1 is overexpressed in multiple myeloma and correlates with increased bone disease and shorter survival, a genome-wide RNA interference screen identified XPO1 as an essential gene required for myeloma cell survival and proliferation." (PMID 34925019, 2021). "Eltanexor (KPT-8602) is a newly developed synthetic second-generation XPO1 inhibitor and less toxic than analogs, and is currently in phase I/II clinical trials for multiple myeloma." (PMID 34012430, 2021). "For example, myeloma cells have a high XPO1 expression compared to normal plasma cells, and its expression has been shown to increase with progression, to be associated with increased lytic bone lesions and shorter survival." (PMID 32624581, 2020). "Selinexor was the first slowly reversible XPO1 inhibitor to enter clinical development and is currently marketed for third line treatment of multiple myeloma in combination with dexamethasone." (PMID 32545904, 2020). "Bioinformatic studies show that RCC2 is associated with Exportin-1 (XPO1), which is a crucial factor in a complex mechanism of bortezomib resistance in multiple myeloma." (PMID 33521058, 2020). "One of the most promising, Selinexor, targets exportin 1 (Xpo1) and is currently in pre-clinical trials and has shown efficacy against acute myeloid leukemia and multiple myeloma." (PMID 30906315, 2019). "Other investigators have also reported that XPO1 inhibition leads to the suppression of various tumors such as multiple myeloma, lymphoma, lung, breast, ovarian and other cancers." (PMID 31382411, 2019). "We have shown that knockdown of exportin 1 (XPO1/CRM1) protein by siRNA or with an XPO1 inhibitor will sensitize drug-resistant myeloma cells to the topoisomerase II (TOP2) inhibitor doxorubicin." (PMID 27806331, 2016). "In our previous studies, we have shown that knockdown of exportin 1 (XPO1) protein by siRNA or inhibition with an XPO1 inhibitor will sensitize drug-resistant myeloma cells to the topoisomerase II (TOP2) inhibitor doxorubicin." (PMID 27557643, 2016). "XPO1 inhibitors, when used in combination with the proteasome inhibitors (PI) bortezomib and carfilzomib, were found to synergistically kill multiple myeloma (MM) cells and when co-cultured with bone marrow stromal cells." (PMID 27806331, 2016). "XPO1 inhibition by selinexor is approved for second-line treatment of multiple myeloma." (PMID 40148556, 2025). "Thus, nuclear–cytoplasmic shuttling currently represents an attractive therapeutic target investigated in different tumor types, as recently demonstrated by the Food and Drug Administration approval of the exportin 1 inhibitor selinexor for multiple myeloma." (PMID 40724843, 2025). "XPO1, is overexpressed in multiple myeloma (MM) cells and is essential for myeloma cell survival." (PMID 38541708, 2024).
multiple myeloma (continued). "Newer classes of anti-myeloma agents approved in recent years, including selinexor (an inhibitor of exportin 1), Teclistamab (BCMA-redirected bispecific T cell engager), and belantamab mafodotin (an antibody-drug conjugate targeting BCMA), have reported median PFS between 3.7 to 11.3 months." (PMID 38659046, 2024). "Furthermore, following clinical trials, inhibition of XPO1 is gaining traction as a cancer therapeutic target and is now licensed for multiple myeloma and diffuse large B cell lymphoma." (PMID 39178254, 2024). "The XPO1 inhibitor KPT-330 has been approved for the treatment of multiple myeloma." (PMID 37500615, 2023). "XPO1 knockdown in myeloma cell lines reestablished sensitivity to proteasome inhibitor." (PMID 35091658, 2022). "Notably, the XPO1 inhibitor selinexor can be used for the treatment of multiple myeloma and DLBCL, and the FDA has approved selinexor for adult patients with r/r DLBCL 35-37." (PMID 34405005, 2021). "Moreover, with the identification of novel targets, new drug classes have entered the myeloma armamentarium, such as XPO1 inhibitors (selinexor), HDAC inhibitors (panobinostat), and anti-BCL-2 agents (venetoclax)." (PMID 34680358, 2021). "The therapeutic efficacy of XPO1 inhibition in patients has led to FDA approval of selinexor for the treatment of patients with multiple myeloma and DLBCL in the USA, and conditional marketing authorization by the European Commission for patients with multiple myeloma." (PMID 34926302, 2021). "Therefore, XPO1 has been identified as an oncogenic target and an inhibitor against XPO1 has been approved for the treatment of multiple myeloma." (PMID 32612949, 2020). "Due to the tremendous impact of the inhibitor of Xpo1 in multiple myeloma, we may expect that targeting the nuclear-cytoplasmic machinery may be translated into Ph+ leukemias to provide new therapeutic chances." (PMID 31614958, 2019). "High expression of XPO1 has been found in many types of solid and hematopoietic malignant tumors including cervical cancer, prostate cancer, ovarian cancer, pancreatic cancer, gastric cancer, osteosarcoma, glioma, multiple myeloma, lymphoma and leukemia." (PMID 30450161, 2018). "The combination of an XPO1 inhibitor and liposomal doxorubicin appears highly effective in in vitro resistant MM models, xenograft studies, and ex vivo samples from patients with relapsed/refractory myeloma." (PMID 28196522, 2017). "Multiple myeloma (MM) cells have a higher XPO1 expression than bone marrow normal plasma cells and cells from monoclonal gammopathy of unknown significance (MGUS) patients." (PMID 28196522, 2017). "The combination of an XPO1 inhibitor and liposomal doxorubicin was highly effective against acquired drug resistance in in vitro MM models, in in vivo xenograft studies, and in ex vivo samples obtained from patients with relapsed/refractory myeloma." (PMID 27557643, 2016). "In addition, XPO1 inhibitors were found to reverse de novo drug-resistance of multiple myeloma (MM) cells in high-density cell culture models and drug resistance conferred to MM cell lines when co-cultured with bone marrow stromal cells." (PMID 27557643, 2016). "We found that the combination treatment of an XPO1 inhibitor (selinexor) and a PI (bortezomib) synergistically increased IκBα more than single-agent selinexor or bortezomib treatment in both parental and PI-resistant MM cell lines and in patient myeloma cells." (PMID 27806331, 2016). "Similarly, human myeloma cells treated with the reversible XPO1 inhibitor CBS9106 exhibited downregulation of protein that was dependent on the ubiquitin/proteasome pathway." (PMID 25022346, 2014). "Upregulation of XPO1 is observed in many types of cancer tissues such as lung cancer, osteosarcoma, pancreatic cancer, ovarian cancer, cervical carcinoma, gastric and hepatocellular carcinoma, myeloid and lymphoid leukemia, mantle cell lymphoma, and multiple myeloma tissues." (PMID 31088931, 2019).
multiple myeloma (continued). "Selinexor, a selective inhibitor of exportin 1 (XPO1), is a U.S. Food and Drug Administration (FDA)-approved medication for the treatment of multiple myeloma." (PMID 41155531, 2025). "Furthermore, co‐treatment with venetoclax and the XPO1 inhibitor, selinexor, showed enhanced efficacy in myeloma cells under hypoxic conditions, indicating that this combination therapy may be a promising approach for targeting myeloma cells in the hypoxic BM niche." (PMID 40539846, 2025). "XPO1, a nuclear exporter and secreted protein, has been approved by the United States Food and Drug Administration (US FDA) for multiple myeloma." (PMID 39372390, 2024). "The first-in-class XPO1 inhibitor selinexor, has shown anti-proliferative effect both in vivo and in vitro in AML and myeloma, and is approved for the treatment of myeloma." (PMID 35152270, 2022). "Research showed that SINE compounds, such as the first-generation XPO1 inhibitor Selinexor (KPT-802), approved by the FDA for multiple myeloma therapy can induce apoptosis in GBM cells and respective animal models without overt evidence of neurotoxicity." (PMID 36140245, 2022). "Initial screening studies supported targeting XPO1 with KPT-330 (trade name selinexor), which is an FDA-approved therapeutic for multiple myeloma and lymphoma." (PMID 34628286, 2021). "Selinexor is an inhibitor of XPO1 and was approved by FDA for use as a treatment for refractory multiple myeloma and lymphoma." (PMID 34829820, 2021). "High XPO1 expression also supports NF-kB signaling, a key feature in many hematological malignancies, including non-Hodgkin lymphoma, CLL and multiple myeloma." (PMID 32624581, 2020). "Selinexor acts by inhibiting the nuclear export protein, exportin 1, and has received FDA approval for the treatment of multiple myeloma in the U.S.." (PMID 32560115, 2020). "XPO1 is frequently overexpressed and deregulated in various human cancer entities (e.g., in sarcoma, DLBCL, multiple myeloma, KRAS-mutant lung cancer, pancreatic, ovarian, glioma, lung, gastric, prostate, and colorectal cancers) and is associated with poor prognosis." (PMID 36140245, 2022). "When gating on the CD138/light-chain double-negative non-myeloma cells, we found that they were not sensitized to apoptosis by XPO1 inhibitors." (PMID 27806331, 2016). "In contrast, CD138/light-chain double-negative non-myeloma cells from the same patient bone marrow aspirates were not sensitized to apoptosis by XPO1 inhibitors." (PMID 27557643, 2016).